TNF (tumor necrosis factor)
Diseases named in the same sentence as TNF in open-access papers (continued):
Sharing a sentence is not in itself a finding about the gene and the disease.
periodontal disease (continued). "RA and periodontal disease share many similarities in etiology and pathogenesis, and both are characterized by excessive production of inflammatory cytokines such as TNF and IL-6." (PMID 36294882, 2022). "In periodontal disease, the cytokines IL-1, TNFα und IL-6 activate osteoclasts via RANKL, resulting in increased resorption of the alveolar bone." (PMID 33771147, 2021). "IL-1α, IL-1β, and TNF-α as predictive biomarkers for the diagnosis of periodontal disease were analyzed by ROC curves." (PMID 34199256, 2021). "A recent study showed that levels of IL-1β, TNF-α, and other inflammatory cytokines can be used to accurately monitor the progress, treatment effectiveness, and prognosis in periodontal disease." (PMID 34299815, 2021). "Here, we examined the therapeutic effect of TNF-α preconditioned-GMSC-derived exosomes on periodontal disease, and tried to unveil detailed molecular mechanisms." (PMID 33359765, 2021). "In an LPS-induced rat model of periodontal disease, hydrogen peroxide and TNF-α significantly increased in the epithelium of diseased tissues." (PMID 33995107, 2021). "In the case of periodontal disease, several inflammatory molecules are released, such as IL-1β, IL-6, interleukin-8 (IL-8), LPS, TNF-α, and PGE2." (PMID 34833990, 2021). "High levels of IL-1, TNF-α, and IL-6 have been also found in the gingival crevicular fluid and plasma of patients with periodontal disease." (PMID 34199256, 2021). "This is unlikely to be reflective of this specific MAO-A/B inhibitor because phenelzine did reduce TNF-α expression in an in vivo animal model of LPS-induced periodontal disease." (PMID 33995107, 2021). "For example, several pro-inflammatory cytokines and Tumor Necrosis Factor-α (TNF-α) are elevated in AD patients with periodontal disease." (PMID 35056505, 2021). "Expression of genes encoding tumor necrosis factor (TNF) and its receptor superfamilies’ (TNFSF and TNFRSF) have decisive role in autoimmune, respiratory, periodontal diseases etc." (PMID 33344663, 2020). "During periodontal disease, host inflammatory cells are recruited, and inflammatory cytokines, such as IL-1β, IL-6, and TNF-α, are released from fibroblasts, macrophages, connective tissue, and junctional epithelial cells." (PMID 33383828, 2020). "Among other factors, alteration of the lipid profile, which is characteristic of PCOS patients, triggers the release of proinflammatory cytokines such as TNFα, thereby contributing to the pathogenesis of periodontal disease." (PMID 32456146, 2020). "Tumour necrosis factor α (TNFα) and interleukin (IL)-6 represent proinflammatory cytokines that modulate the inflammatory response during periodontal disease." (PMID 32456146, 2020). "As a sequela of periodontal disease, pro-inflammatory mediators such as interleukin-1 (IL-1, 6, 8), tumor necrosis factor (TNF-α) are produced." (PMID 33227918, 2020). "The estimation of the levels of TNF-α as an inflammatory marker in periodontal diseases in this group of patients seems of limited value due to the presence of systemic inflammation, as confirmed by other authors." (PMID 33202617, 2020). "Particularly, many clinical studies have demonstrated the correlation between high TNF-α and IL-6 expressions and periodontal disease, highlighting their involvement and crucial role in the evolution of gingival inflammation." (PMID 33096800, 2020). "During disease-induced chronic inflammation, such as that in periodontal disease, TNFα and CHX led to altered bone remodeling." (PMID 31637258, 2019). "TNF, IL-6 and IL-17 have multiple overlapping functions that contribute to RA and periodontal disease by stimulating leukocyte activation and migration, chemokine expression and bone resorption." (PMID 31182740, 2019). "In humans, concentrations of IL-1, IL-6 and TNF-α in the gingival crevicular fluid are known to contribute to acute and chronic inflammation in periodontal disease." (PMID 30822336, 2019).
periodontal disease (continued). "Many mediators of inflammation in periodontal disease are associated with cancer risk, such as C-reactive protein (CRP), Matrix metalloprotenases (MMP), Tumor Necrosis Factor (TNF), and Interluekin (IL)." (PMID 30754693, 2019). "Several proinflammatory cytokines that are elevated in periodontal disease, such as tumor necrosis factor alpha (TNF-α) and interleukin- (IL-) 6, have been shown to stimulate osteoclastogenesis." (PMID 31637266, 2019). "The concentration of pro-inflammatory cytokines such as IL-6 and TNF-α in gingival crevicular fluid (GCF) increases with the progress of periodontal disease." (PMID 30574217, 2018). "Saliva, as a pooled sample, contains specific biomarkers for unique pathological aspects of periodontal disease, such as interleukin-1β (IL-1β), IL-6, IL-8, IL-11 and tumor necrosis factor-alpha (TNF-α)." (PMID 29740515, 2018). "Patients with periodontal disease showed higher levels of cytokines (IL-2, IL-6, IL-10, and TNF-α) and PGE2." (PMID 30154640, 2018). "Specifically, the close relevance of the cytokine ‘tumor necrosis factor-α' (TNF-α) in DM and debilitating periodontal diseases has been observed." (PMID 30186882, 2018). "During chronic inflammation from diseases, such as periodontal disease, the proinflammatory cytokines interferon-gamma (IFNγ) and tumor necrosis factor-α (TNFα) alter bone remodeling." (PMID 30158833, 2018). "Periodontal disease, with its local and systemic bacterial load, can also trigger a systemic inflammatory response with increased inflammatory cytokines (TNF-α, IL-1, and IL-6) and inflammatory mediators (PGE2) to become a risk factor of preterm delivery." (PMID 30154640, 2018). "Similar to our result, in Ulker, Ng, and Aurer studies, patients with periodontal disease were reported to have lower level of TNF-α." (PMID 29238418, 2017). "Periodontal disease mainly occurs as a result of the activation of host‐derived immune and inflammatory mechanisms induced by cytokines, including IL‐1β, IL‐6, and TNF‐α (2009; 1996)." (PMID 29744190, 2017). "There are two possible pathways for liver injury by periodontal disease, a direct pathway by periodontopathic bacteria and an indirect pathway by cytokines including TNF-α induced by bacteria and lipopolysaccharides." (PMID 28431542, 2017). "β-glucan was also efficient in decreasing the serum levels of TNF-α in diabetic animals with periodontal disease and IL-10 levels in animals with periodontal disease." (PMID 28906456, 2017). "The levels of inflammatory mediators (IL-1β, IL-6, β-glucuronidase, and TNF-α) in saliva and in serum (except IL-6) significantly increased with severity of periodontal disease." (PMID 29017560, 2017). "Among the host mediators produced after microbial recognition, innate immunity cytokines such as TNF-α, IL-1, and IL-6 were the first to have their roles in periodontal disease pathogenesis unraveled." (PMID 28632755, 2017). "TNF-α-induced inflammation signals are believed to be important signals for development of periodontal disease." (PMID 28937990, 2017). "The severity of periodontal tissue inflammation can be estimated by measuring proinflammatory indicators such as IL-1, -6, and -8 and TNF-α that have an important role in the pathogenesis of periodontal diseases." (PMID 28074077, 2016). "Similar to TNFα, IL-1β is a pro-inflammatory cytokine critical to inflammatory response against pathogens that is well known for involvement in periodontal disease." (PMID 27386246, 2016). "At present, numerous potential surrogate measures of existing periodontal disease and oral health have been identified and include cytokines and MMPs such as interleukin-1β (IL-1β), tumor necrosis factor (TNF)-α, and matrix metalloproteinase (MMP)-8." (PMID 25915398, 2015). "Consistent with our data, it has been shown that GSNO, by reducing iNOS, reduces TNF-α expression in a rat model of focal cerebral ischemia and in experimental periodontal disease in rats." (PMID 25478918, 2014).
periodontal disease (continued). "Telmisartan and Olmesartan significantly reduced pro-inflammatory cytokines such as IL-1β and TNF-α, which resulted in significant preservation of bone in periodontal disease." (PMID 24819928, 2014). "Our study suggests that polymorphisms in the IL-4 gene not only affect the production of the IL-4 cytokine but can influence production of several other cytokines, such as IL-10, IFNγ, IL-1β, IL-6, and TNFα, which in turn can affect periodontal disease." (PMID 25530681, 2014). "TNF-α is one of the key periodontal pathogens-induced early inflammatory cytokines in destructive periodontal disease." (PMID 24068858, 2013). "Based on studies like these, it can be projected that TNF-α plays a role in controlling the expression of the cytokines that stimulate bone resorption during periodontal disease." (PMID 24151615, 2013). "During the pathogenesis of periodontal disease, the host immunoinflammatory response to plaque bacteria produces destructive cytokines such as TNF-α, IL-1β, and MMPs." (PMID 24453415, 2013). "In patients with periodontal disease, monocytes and dendritic cells within local periodontal tissues secrete various inflammatory mediators, including IL-1β, IL-6, and TNF-α." (PMID 23951003, 2013). "Increased levels of TNF-α contribute to the onset of destructive periodontal disease via several mechanisms." (PMID 24068858, 2013). "A number of inflammatory mediators, such as interleukin (IL)-1, IL-6, IL-8, tumor necrosis factor-α (TNF-α), prostaglandins and matrix metalloproteinases (MMPs) are involved in periodontal diseases." (PMID 24137277, 2013). "TNF-α plays an important role in periodontal disease as demonstrated by human studies that show an increased expression TNF-α during periodontal breakdown." (PMID 24151615, 2013). "In this study, using a model of periodontal disease, animals treated with 10 mg/kg of Atorvastatin also had reduced levels of TNF-α and IL-1β." (PMID 24130702, 2013). "In patients with periodontal disease, TNF-α expression was elevated in the GCF at sites where bone and attachment loss have just occurred." (PMID 24151615, 2013). "Clinical evidence indicates that patients with periodontal disease have increased TNF-α in the gingival crevice fluid, and TNF-α has been shown to be enhanced during destruction of periodontal tissues." (PMID 22315682, 2012). "To date, two proinflammatory cytokines, TNF-α and IL-1β, are the best understood cytokines that correlate significantly with periodontal diseases." (PMID 22315682, 2012). "The data from this study revealed that treatment with an orally active p38 MAPK inhibitor stopped the established periodontal disease progression in vivo and decreased inflammatory cytokine (IL-1β, TNF-α) expression and osteoclastogenesis." (PMID 22315682, 2012). "There is evidence to suggest that TNF-α plays a central role in the pathogenesis of periodontal disease." (PMID 20607056, 2010). "Macrophages are known to be the main producer of TNF-α and a dense infiltration of inflammatory cells, including macrophages, occurs in the gingival connective tissues of patients with periodontal disease." (PMID 20607056, 2010). "Anticytokine therapy for periodontal diseases mainly targets TNF-α, IL-1β, and IL-6, because they are essential for the initiation of inflammatory immune reactions and are produced for prolonged periods in inflammatory disease." (PMID 20407652, 2009). "Treating periodontal disease reduces pro-inflammatory mediator levels such as IL-6, tumor necrosis factor-α (TNF-α), CRP, and reactive oxygen species (ROS) and increases pro-resolving lipid mediators, which are anti-inflammatory in nature and help maintain homeostasis." (PMID 40916006, 2025). "Hyperglycemia can worsen periodontal disease in diabetic patients by affecting TNF-α levels." (PMID 41244040, 2025).
periodontal disease (continued). "NGAL expression can be stimulated by many cytokines and growth factors that may contribute to periodontal diseases, such as interleukin-1, IL-17, IL-22, insulin-like growth factor-1, transforming growth factor alpha, and tumor necrosis factor-alpha." (PMID 41040472, 2025). "In addition, elevated levels of salivary IL-1β, IL-6, and TNF-α reflect activation of the local inflammatory response, which is consistent with previous studies on salivary biomarkers in periodontal disease." (PMID 41301927, 2025). "Periodontal disease is clearly related to elevated TNF-α levels." (PMID 40426985, 2025). "Considering this hypothesis and taking into account that periodontal disease can directly contribute to the peripheral inflammatory environment, the impact of flavonoids on TNF-α seems reasonable." (PMID 40430449, 2025). "Additionally, inflammatory biomarkers such as IL-17, TNF-α, and IL-6 highlight direct links between local periodontal disease and systemic inflammation." (PMID 40076622, 2025). "Regarding periodontal disease, TNF-α is a crucial biomarker that may facilitate diagnosis, prognosis, and treatment." (PMID 40426985, 2025). "Furthermore, other downstream cytokines, including IL-2, IL-8, TNF-α, and IL-13, were also statistically significantly (p < 0.05) increased as periodontal disease severity increased, supporting a heightened inflammatory response." (PMID 41303313, 2025). "The first mechanism is supported by the presence of periodontal disease bacteria formed in atherosclerotic lesions in the coronary arteries and the second by the presence of increased levels of IL-1b, IL-6, IL-8 and TNF-a which are cytokines also related to ASCVD26." (PMID 41006734, 2025). "Gingival crevicular fluid levels were found to be affected by disease status, indicating that the TNF-α/HIF-1α/VEGF pathway might play a role in periodontal disease pathogenesis." (PMID 39822781, 2024). "Another significant mechanism of ROS involvement in periodontal disease involves the activation of cytokines (TNFα and Interleukin-1), chemokines (Interleukin-8), and cell adhesion molecules, leading to accelerated cellular apoptosis through DNA damage caused by nitroxyl radicals (NO)." (PMID 38338704, 2024). "On the other hand, inflammatory cytokines generated during periodontal disease, such as TNF-α and interleukins (IL-1, IL-6), could penetrate the systemic circulation and exacerbate the inflammatory condition linked to OSA." (PMID 39061956, 2024). "Patients with severe, untreated, periodontal disease exhibited elevated levels of pro-inflammatory mediators, such as IL-1, IL-6, tumor necrosis factor-alpha (TNF-α), and prostaglandin E2 (PGE2), which entered the systemic circulation, triggering an acute-phase response as observed previously." (PMID 39587593, 2024). "On a more detailed level, there is evidence that periodontal disease could increase circulating levels of certain pro-inflammatory cytokines, including IL-6, IL-1β, and TNF-α, that were also found to be upregulated in serum samples of men with prostatitis." (PMID 37046667, 2023). "Overall, our results showed selective inhibition of IL-1β, TNF-α, IL-8, MMP-2, and MMP-9 associated with hesperidin, which could represent a promising novel approach to the treatment or prevention of periodontal disease." (PMID 37373533, 2023). "Moreover, by decreasing the salivary levels of MMP-8 and plasma levels of IL-1 and TNF-α, the biomaterial showed an immunomodulatory effect on the local and systemic biomarkers of the periodontal disease." (PMID 36840029, 2023). "Salivary cytokines, particularly IL-1β, IL-6, and TNF-α, can serve as reliable markers for periodontal disease severity and may aid in monitoring disease progression." (PMID 38192959, 2023). "In addition, pre-inflammation cytokines, including IL-6, IL-17, IFN-γ, TNF-α, and other inflammatory molecules, were reported to elevate in the serum of periodontal disease patients." (PMID 37181367, 2023).
periodontal disease (continued). "Thus, the aim of this study was to explore for the first time the involvement of miR-15a-5p, miR-23a-3p, miR223-3p, miR-103a-3p, miR-423-5p and TNFα, IL-6 production in periodontal disease pathological and healthy GCF." (PMID 36599866, 2023). "Excessive pro-inflammatory cytokines and some inflammatory mediators were found in periodontal disease including TNF-α, IL-6, and IFN-γ could quantify the acute or chronic inflammatory responses after the administrations of MitoQ@PssL NPs." (PMID 36588945, 2022). "Increased levels of TNF-α are part of the pathogenesis of infection through the mechanism of phagocytic cells, as polymorphonuclear, neutrophil, monocytes, and macrophages will trigger the release of chemical mediators such as TNF-α cytokines that play a role in periodontal disease." (PMID 35178093, 2022). "It plays a paramount role in periodontal disease and alveolar bone destruction by producing proinflammatory mediators such as IL-1β, IL-6, and TNF-α, which are multifunctional cytokines produced by lymphocytes, monocytes, and fibroblasts with extensive biological activities." (PMID 35911651, 2022). "In a recent study that evaluated the relationship between oral health, insulin resistance and resistance training in rats, it was observed that periodontal disease promoted a decrease in insulin sensitivity, due to the release of inflammatory mediators, such as the tumor necrosis factor-α (TNF -α)." (PMID 35029853, 2022). "Similarly, TNF-α release was higher from oral blood of patients with periodontal disease when compared to healthy controls." (PMID 33672708, 2021). "RA patients with persistent periodontal disease have shown less responsiveness to anti-tumor necrosis factor alpha (anti-TNFα) treatment, and it is reported that periodontal treatment may reduce RA disease activity." (PMID 33674638, 2021). "Our recent findings suggest that blockade of TNF-α may be beneficial for periodontal diseases in SLE patients." (PMID 33861790, 2021). "Moreover, numerous studies have reported a positive relationship of periodontal disease morbidity with inflammatory cytokines, including tumor necrosis factor, interleukin (IL)-1, IL-6, and IL-8, which are involved in arteriosclerosis." (PMID 34262126, 2021). "Periodontal diseases being inflammatory pathologies, they induce the production of inflammatory mediators such as tumor necrosis factor α (TNF-α), interleukins (IL-1, IL-6, IL-8) and the C-reactive protein (CRP) that have been shown to be associated with atherogenesis." (PMID 33575410, 2021). "However, in the 11 studies included in this study, IL-1β, MMP-8 and TNF-α in saliva were the most frequently observed biomarkers in periodontal disease patients compared to healthy controls." (PMID 33383828, 2020). "Therefore, the presented results need to be confirmed by further studies, which including assessment of hand dexterity, dental caries, periodontal diseases and inflammation cytokines such as IL-6 and TNF-alpha." (PMID 32649678, 2020). "The disturbance of the lipidic metabolism could be explained by the inhibition of the lipase lipoprotein secondary to the release of pro-inflammatory cytokines, such as IL-1β and TNF-α during periodontal diseases." (PMID 31640685, 2019). "Interstudy variation in TNF-α concentrations may be due to several factors including periodontal disease severity, subject age, sample type, population type, and technique details such as storage temperature and pretest storage time." (PMID 31355282, 2019). "TNF and IL-1β are well-known key cytokines for periodontal disease." (PMID 31921182, 2019). "Based on these observations, TNF-α and IL-8 expression in the periodontal pocket is speculated to play crucial roles in the pathogenesis, development, and immune response to periodontal disease in HD patients." (PMID 31382656, 2019).